APP (amyloid beta precursor protein)
Diseases named in the same sentence as APP in open-access papers (continued):
Sharing a sentence is not in itself a finding about the gene and the disease.
amyloid (continued). "These mice, which express APP and TAU variants of human genes in the brain, have been shown to recapitulate with aging the combined amyloid and TAU pathology of the human disease." (PMID 35628609, 2022). "As immunostaining results show age-progressive amyloid deposition in hippocampal CA1 in APP-KI mice, our monosynaptic rabies virus tracing reveals pathological impairments of excitatory CA1 cell input connectivity." (PMID 35843448, 2022). "A study of three transgenic genotypes (APP, PS/APP, and PS; >12 months of age) reported that all three models exhibited decreased T2 relaxation values in the cortex and hippocampus, and that amyloid deposition was correlated with the largest T2 reductions." (PMID 35203515, 2022). "The results showed that RP1 reduced the expression of APP and β-secretase, thereby reducing the formation and accumulation of Aβ, improving memory impairment, and reducing amyloid plaque load in the mouse model." (PMID 35209007, 2022). "According to these studies, Sortilin thus has a neuroprotective feature against APP-dependent amyloidosis likely because it consequently decreases the cleavage of cytotoxic sAPPβ." (PMID 36397124, 2022). "We utilized APOE knock-in mice capable of having APOE selectively removed from astrocytes in a tamoxifen-inducible manner and crossed them with the APP/PS1-21 mouse model of amyloidosis." (PMID 35109920, 2022). "In the APP/PS1 model with only amyloid pathology, TMEM119 levels significantly increased with the repopulation of microglia in males but not in females." (PMID 35787714, 2022). "In our previous study, we have identified that CIP2A is upregulated in AD brains and promotes AD-like tauopathy and amyloidosis through inhibiting PP2A’s dephosphorylating effects on tau/APP." (PMID 35286657, 2022). "Mutations to both APP and PSEN1/ PSEN2 have been shown to result in mouse models that develop faster and more aggressive amyloidosis than the single APP mutation models as well as earlier cognitive decline and neuronal loss." (PMID 36359298, 2022). "Astrocytes from APP/PS1/LRP1-KO mice also exhibited impaired clearance capacity together with amyloid accumulation." (PMID 35628216, 2022). "The 6E10+4G8 antibodies targeting respectively amino acids 1–17 and 18–23 of the APP Aβ region, were mixed and used to investigate the presence of amyloid plaque." (PMID 36438008, 2022). "In particular, in a scenario where LDL receptor roles are clear in the cholesterol metabolism and in the amyloidosis, given their interaction with APP, the corresponding roles of the purinergic receptors need to be further clarified." (PMID 35955821, 2022). "BACE-1 is the enzyme degrading amyloid precursor protein (APP), leading to accumulation of amyloid plaques, another significant hallmark of neuropathological lesions in AD brain." (PMID 35161275, 2022). "It was already demonstrated that knocking out CD33 results in lower Aβ levels and reduced amyloid plaque burden in the brain of APP(Swe)/PS1(ΔE9)/CD33KO mice." (PMID 35327591, 2022). "The Aβ peptide is a 39–43 amino acid residue peptide, a regular secretion product of the metabolism of transmembrane protein APP, which is mainly processed in two ways: amyloidosis and non-amyloidosis." (PMID 35904705, 2022). "Mating this allele with a CreER driver allows both spatial and temporal control over APP expression, and with it, amyloid onset." (PMID 35394029, 2022). "Regarding the Bcl-2, increased levels are well described in AD brains and in amyloid containing brain regions of mice overexpressing APP." (PMID 35810220, 2022). "Amyloidosis is also accelerated in atherogenic diets in an animal model of pre-symptomatic AD consisting of amyloid precursor protein/presenilin 1 (APP/PS1) mice." (PMID 35634148, 2022). "Intriguingly, miR-342-5p enrichment in Exo-APP ameliorated amyloid pathology in the recipient cells." (PMID 36497090, 2022).
amyloid (continued). "Crucially, the modified miR-342-5p-enriched Exo-APP ameliorated amyloid pathology in the recipient neuron cells compared with the naïve Exo-APP." (PMID 36497090, 2022). "We focused on the APP processing and Aβ plaque deposition in the brain and described the regulation of autophagy in Nmnat-facilitated clearance of amyloid aggregation." (PMID 35401143, 2022). "Amyloid plaques are composed of abnormal aggregated forms of the amyloid β-proteins (Aβ) that are generated normally by enzymatic cleavage from the amyloid precursor protein (APP)." (PMID 35862308, 2022). "In general, these models develop an accelerated and more aggressive amyloidosis than the single APP-based models do, accompanied by an earlier appearance of the other classical cognitive and histopathological hallmarks." (PMID 35628216, 2022). "Some of the genes in EADAM have been observed in other mouse models of amyloidosis that show early AD-like pathology, including APP;PS1 and 5xFAD mouse models." (PMID 36536457, 2022). "A previous report showed the beneficial effect of selective 5-HT2A receptor (5-HT2AR) antagonism against microglial dysfunction and amyloid deposition in the APP/PS1 amyloid model of AD." (PMID 35273086, 2022). "Small animal PET imaging using FBB was able to detect Aβ plaques in transgenic amyloidosis models such as APP/PS-21, PS2APP, and NSE-hAPP mice." (PMID 34671235, 2021). "Mutations in genes encoding amyloid precursor protein (APP), presenilin 1 (PS1) and presenilin 2 (PS2) that promote amyloidosis and/or tauopathy are closely associated with the development of familial AD (FAD)." (PMID 33557250, 2021). "Amyloid plaques are mainly formed by amyloid peptides of 36‐43 amino acids deriving from cleavage of amyloid precursor protein (APP) by beta‐ and gamma‐secretases." (PMID 34338436, 2021). "Our previous work showed that this BBB-penetrating TNF-α inhibitor reduces Aβ plaques, insoluble Aβ1-42, BBB-disruption, brain endothelial activation, and cognitive memory deficits in the APP/PS1 double transgenic AD mouse model of amyloidosis." (PMID 34972522, 2021). "APP expression is downstream from the FMRP cascade, and patients with FXS are characterized by increase in APP level and concomitant accumulation of amyloid plaques." (PMID 34760921, 2021). "NgR knockdown APP/PS1 mice showed simultaneous reduced amyloid burden and improved spatial learning and memory, which were associated with increased Aβ clearance." (PMID 34821024, 2021). "To determine the impact of reducing Arg1 in a mouse model of amyloidosis, we obtained 33 DEGs (p < 0.05) in comparison of APP/Arg1 insufficient mice to APP/Arg1 sufficient mice." (PMID 34046031, 2021). "Previously we sought to investigate the impact of reduced myeloid Arg1 in the APP Tg2576 mouse model of amyloidosis." (PMID 34046031, 2021). "The regional expression of the APP gene has been shown to be positively correlated with the severity of regional amyloid deposition observed in PET studies." (PMID 35002653, 2021). "We used male and female wild-type control (C57BL/6J) mice to compare to two well-characterized amyloidosis models of AD, APP/PS1, and AppNL-G-F." (PMID 34299071, 2021). "Cytotoxic assays on primary neurons derived from transgenic 5xFAD mice were also performed, since cultured neurons from AD transgenic animal models express APP metabolites involved in amyloid pathology and can reflect AD phenotypes in vitro." (PMID 34608607, 2021). "The high concentrations of iron in cells promote the cleaving of APP through amyloidosis pathway, in which APP undergoes β and γ secretases cleavage to form Aβ1–40 and Aβ1–42 fragments." (PMID 34830326, 2021). "Furin can enhance the activity of α secretory enzymes, and high concentrations of iron in cells reduce furin enzyme activity, leading to the amyloidosis pathway of APP cleaving." (PMID 34830326, 2021).
amyloid (continued). "While APP/KI and APP/PS1 mouse models of amyloidosis have been tested in the IntelliCage, to date, the 3xTg-AD model has not been evaluated in this automated behavioral phenotyping apparatus." (PMID 34483889, 2021). "LRGT reduced amyloid plaque burden in the APP/PS1 animals (p < 0.001), as well as Aβ aggregates levels (p = 0.046), and tau hyperphosphorylation (p = 0.009) in the APP/PS1xdb/db mice." (PMID 34975451, 2021). "The mitochondrial dysfunction is mediated by the accumulation of anomalous tau in the mitochondria, which takes place in the presence of amyloid in the APP/PS1 model." (PMID 34769380, 2021). "Targeting FT directly by the genetic approach, we have reported that systemic FT haplodeficiency rescues cognitive function in addition to reducing amyloid pathology in APP/PS1 mice." (PMID 34315531, 2021). "Amyloid precursor protein (APP) transgenic mouse models show that endogenous tau in CSF increases during the progression of amyloid plaque formation, accompanied by hyperexcitable neurons." (PMID 33672982, 2021). "APP/PS1/Aβ-Th17 mice showed total amyloid plaque loads 32% and 37% greater than APP/PS1 controls in cortex and hippocampus, respectively, but did not attain significance." (PMID 34798897, 2021). "Immunohistochemistry of AD brains confirms that female APP/PS1 mice carry a higher amyloid plaque burden and have enhanced microglial activation compared with male APP/PS1 mice." (PMID 34796608, 2021). "Sex‐specific study of synaptic plasticity and memory reveals female APP/PS1 mice carry a higher amyloid plaque burden and enhanced Iba‐1‐positive microglial activation compared with male APP/PS1." (PMID 34796608, 2021). "APP/PS1 mouse model of AD amyloidosis show an upregulation and activation of A2A adenosine receptors hampering long-term synaptic potentiation (LTP) in hippocampal CA3 pyramidal cells." (PMID 33828485, 2021). "At 10 months of age, we assessed the male APP/PS1 phenotype compared to the APP/PS1;Atase1−/− and APP/PS1;Atase2−/− male mice, evaluating several pathologic hallmarks of AD including amyloid plaque deposition, gliosis, and synaptic loss." (PMID 33846551, 2021). "Microglia from female APP/PS1 mice were glycolytic and less phagocytic and associated with increased amyloidosis whereas microglia from males were amoeboid and this was also the case in post-mortem tissue from male AD patients, where plaque load was reduced." (PMID 34112929, 2021). "Adoptive transfer of Aβ-Th1 and Aβ-Th17 Teffs exacerbated memory impairment and amyloid deposition in APP/PS1 mice." (PMID 34798897, 2021). "Subsequently, the elevated holo-Lf would promote amyloidogenic processing of APP and thus contribute to amyloid pathology." (PMID 34400772, 2021). "Amyloid plaques are extracellular accumulations of amyloid derived from Aβ peptides of various lengths, which are products of Amyloid Precursor Protein (APP) processing (Chen and Mobley, 2019a; Lott and Head, 2019)." (PMID 34276349, 2021). "AICD SUMOylation also decreases amyloid plaques and rescues spatial memory deficits in APP/PS1 mice." (PMID 32950104, 2021). "Female APP/PS1 mice had elevated amyloid-related AD pathologies compared to APP/PS1 males but these pathologies were not exacerbated following irradiation." (PMID 34948098, 2021). "As expected, we found that the amyloid deposits are severely increased in the brains of aged APP/PS1 mice when compared to younger APP/PS1 mice." (PMID 34193971, 2021). "In support of these findings, the reduction of CLU showed opposite results i.e., substantial increase of amyloid plaque load in both cortex and hippocampus of APP/PS1; Clu+/− mice, and in CAA within the cerebrovasculature of APP/PS1; Clu−/− mice." (PMID 34454574, 2021). "TEM analysis demonstrated the scarce presence of synaptic contacts around the amyloid plaques as soon as 4.5 months of age in APP/PS1 mice." (PMID 34803589, 2021).
amyloid (continued). "The fact that supplementation with Ψ-GSH attenuates all of the pathological parameters in aged APP/PS1 models show that reduced brain GSH level is a key driver of amyloid-dependent pathological changes, including progressive degeneration of LC neurons." (PMID 34829667, 2021). "While the variability associated with the utilization of human donor samples is a logical detriment, the ability of human tissue to induce amyloid pathology in APP transgenic mice is clear." (PMID 33588898, 2021). "While we confirm the sensitivity of MMN observation in schizophrenic patients and preclinical PCP models, the present study discloses novel MMN results on the IMI PRISM dataset and the APP/PS1-21 mouse model of amyloidosis." (PMID 33927180, 2021). "The APP/PS1xdb/db mice show brain atrophy and altered amyloid pathology when compared with APP/PS1 mice." (PMID 34975451, 2021). "Amyloid β present in animal models of amyloidosis, such as APP/PS1 mice used here, leads to calcium elevations within a fraction of cortical neurons (arrows and arrowhead)." (PMID 33926907, 2021). "NR treatment restored mitochondrial function and robustly decreased amyloid pathology and improved context-dependent memory in the APP/PS1 mice." (PMID 32471464, 2020). "The effect of elevated CLU levels on amyloid deposition in the brain was assessed 8 months after viral injections, when moderate amyloid pathology is observed in this APP/PS1 amyloid model." (PMID 33246484, 2020). "It is reasonable that reduced amyloid deposition and glial activation leads to improved cognitive function of APP/PS1 mice with less NgR in the perforant path, although the effect of NgR knockdown on cognitive function in wild type mice is not clear." (PMID 32331528, 2020). "Other studies also found the higher expression of astroglial connexin 43 around the amyloid plaques in APP/PS1 mice." (PMID 31868207, 2020). "In the present study, we used multivariate analysis tools to profile brain cytokine protein expression in the APPswe/PS1dE9 (APP/PS1) mouse model of AD amyloid pathology." (PMID 31992349, 2020). "As well as γ-secretase’s role in cleaving the NICD, it is also involved in cleavage of the amyloid precursor protein (APP); increased cleavage of APP into toxic Aβ fragments leads to the production of amyloid plaques, a characteristic feature of AD." (PMID 33348528, 2020). "Clearly, more studies are needed to clarify how Boc2-treatment reduces the amyloid plaque load in APP/PS1 mice." (PMID 32331524, 2020). "One study showed increased microglia activation detected in vivo using positron emission tomography, and a greater amyloid plaque load in APP/PS1 TG mouse which received a high-fat diet and a streptozocin treatment." (PMID 31964387, 2020). "Here we have examined Trem2 effect in an APOE isoform-dependent and amyloid-dependent manner by directly comparing age-matched APP/E3 and APP/E4 mice that are at different stages of amyloid pathology." (PMID 32703241, 2020). "In 5xFAD mice, which express human APP and PSEN1 transgenes with five AD-linked mutations, leading to rapid development of amyloidosis, an increase in the phylum Firmicutes and a decrease in the phylum Bacteroidetes was observed at nine weeks." (PMID 33153085, 2020). "According to previous studies, TFEB overexpression is not only effective on attenuating tauopathy but can also attenuate amyloid pathogenesis by reducing APP and Aβ." (PMID 31858697, 2020). "Amyloid plaques mainly contain the amyloid-beta (Aβ) peptide, which is released by proteolytic cleavage of the amyloid precursor protein (APP; Selkoe, 2001; Hardy and Selkoe, 2002; Selkoe and Hardy, 2016)." (PMID 32523525, 2020). "We found that CLU overexpression resulted in a significant reduction of total and fibrillar amyloid in both cortex and hippocampus in the APP/PS1 mouse model of AD amyloidosis." (PMID 33246484, 2020).
amyloid (continued). "Amyloid plaques form when the amyloid precursor protein (APP) is sequentially cleaved by endogenous proteases, β-protease and γ-protease." (PMID 33153085, 2020). "Amyloidosis, which produces Aβ cleaved from APP by activation of β- and γ-secretase, is known as the representative cause of AD." (PMID 32397362, 2020). "In the current study, by using conditional LysMcre deletion in APP Tg2576 transgenic mice, we are the first to measure the specific effect of reducing Arg1 in myeloid cells in responding to amyloidosis." (PMID 33519806, 2020). "5xFAD is an early onset mouse model of Alzheimer’s disease harboring five AD-associated mutations in human APP and PS1 which causes rapid progression of amyloid pathology due to the increased generation of insoluble Aβ isoforms." (PMID 33003412, 2020). "For example, the key autophagy‐related protein BECN1 (beclin‐1) had been reported to be reduced in the brains from early AD patients, and overexpression of BECN1 reduced amyloid pathology in APP mice." (PMID 31858697, 2020). "The amyloid burden in the piriform cortex of double tg mice was significantly smaller compared with those in APP tg mice." (PMID 33287899, 2020). "Amyloid plaques are aggregates of various amyloid peptides derived from the amyloid precursor protein (APP)." (PMID 32699218, 2020). "At 19 months, female APP+PS1 rats were found to have amyloid deposits and cerebral amyloid pathology." (PMID 33014535, 2020). "Other studies have shown that elevated ER or cytoplasmic calcium increases Abeta production by triggering phosphorylation of APP and tau, indicating intracellular calcium dysregulation exacerbates amyloidosis and tau pathology." (PMID 33271784, 2020). "While significant amyloid pathology was clearly observed in APP transgenic mice at P180, their survival was impaired from early adulthood." (PMID 32557778, 2020). "In the amyloidosis process, APP is cleaved by BACE-1 (member of β-secretase) and generates sAPPβ and CTF-β." (PMID 32397362, 2020). "Amyloid plaques largely consist of the amyloid‐β (Aβ) peptide, which is produced from the amyloid precursor protein (APP) by sequential cleavage of β‐ and γ‐secretases." (PMID 31777182, 2020). "Our present findings support an increase in amyloidosis following CCL2 overexpression in the brain of APP/PS1 mice." (PMID 32508844, 2020). "Similar plaque morphology with less fibrillar Aβ, as observed in APP-KI mice, has also been reported in AD mice deficient for TREM2 or APOE that also have less microglial cells recruited to amyloid plaques and display prominent neuritic dystrophies." (PMID 32510331, 2020). "The major substrates are Notch and the Amyloid Precursor Protein (APP), which respectively play a critical role during development and in the amyloid pathology found in AD." (PMID 33551720, 2020). "We determined to assess how the haploinsufficiency of Arg1 in myeloid cells impacts the brain during amyloidosis using conditional LysMcre deletion in APP Tg2576 transgenic mice." (PMID 33519806, 2020). "In summary, IIV vaccination during the early stage of AD is sufficient to rescue amyloidosis and ameliorate cognitive deficits in APP/PS1 mice." (PMID 32075657, 2020). "APP/PS1 mouse is a model of amyloidosis, however it also reproduces cognitive impairment as well as anxiety, hyperactivity and social interaction impairment." (PMID 33382724, 2020). "Specifically, sustained increase of CLU expression in astrocytes via viral delivery in the APP/PS1 mouse model of amyloidosis led to amelioration of amyloid accumulation and Aβ-mediated neurotoxicity and gliosis." (PMID 33246484, 2020).